SNORD117 (small nucleolar RNA, C/D box 117)
Synonyms: U83
Gene: Small nucleolar RNA gene on chromosome 6 (31,536,374 to 31,536,449, reverse strand). Ensembl gene ENSG00000201785.
Gene Ontology:
Biological process: RNA processing
Cellular component: nucleolus
Homologues: Orthologues: macaque SNORD83 (99% identical), dog SNORD83 (92% identical), pig SNORD83 (92% identical), rabbit SNORD83 (92% identical), mouse Gm25128 (89% identical), rat Snord83 (88% identical), guinea pig SNORD83 (82% identical), zebrafish SNORD83 (79% identical), zebrafish SNORD83 (76% identical), zebrafish SNORD83 (75% identical), tropical clawed frog SNORD83 (72% identical). Paralogues in human: SNORD83 (78% identical), SNORD84 (78% identical).